ZMPSTE24 (zinc metallopeptidase STE24)
Description:
Transmembrane metalloprotease whose catalytic activity is critical for processing lamin A/LMNA on the inner nuclear membrane and clearing clogged translocons on the endoplasmic reticulum. Proteolytically removes the C-terminal three residues of farnesylated proteins. Also plays an antiviral role independently of its protease activity by restricting enveloped RNA and DNA viruses, including influenza A, Zika, Ebola, Sindbis, vesicular stomatitis, cowpox, and vaccinia. Mechanistically, controls IFITM antiviral pathway to hinder viruses from breaching the endosomal barrier by modulating membrane fluidity.
Synonyms: FACE-1; FACE1; STE24; Ste24p; HGPS; PRO1; RSDM1
Tractability: Small molecule: a structure with a bound ligand is known. Antibody: UniProt predicts a signal peptide or a membrane-spanning region. PROTAC: ubiquitination databases record sites on it; its protein half-life has been measured.
Target class: Metallo protease M48A subfamily; Metallo protease MAE clan; Enzyme; Protease; Metallo protease
Gene: Protein-coding gene on chromosome 1 (40,258,041 to 40,294,180, forward strand). Ensembl gene ENSG00000084073.
Subcellular location: Endoplasmic reticulum membrane; Nucleus inner membrane; Early endosome membrane; Late endosome membrane
Gene Ontology:
Molecular function: endopeptidase activity; protein binding; zinc ion binding; metalloexopeptidase activity; double-stranded DNA binding; metalloendopeptidase activity; metallopeptidase activity; peptidase activity
Biological process: protein maturation; regulation of defense response to virus; CAAX-box protein processing; proteolysis; nuclear envelope organization
Cellular component: early endosome membrane; endoplasmic reticulum membrane; extracellular exosome; late endosome membrane; membrane; nuclear inner membrane; protein-containing complex; nuclear envelope
Genetic constraint (gnomAD): Loss-of-function variants: 44 observed, 52.43 expected, observed/expected ratio (o/e) 0.84, 90% interval 0.66 to 1.08. The upper end of that interval is the gene's LOEUF score, 1.08, which puts it in group 4 of 6, group 1 being the genes least tolerant of losing a copy. Missense variants: 493 observed, 563.62 expected, observed/expected ratio (o/e) 0.87, 90% interval 0.81 to 0.94. Synonymous variants: 169 observed, 203.45 expected, observed/expected ratio (o/e) 0.83, 90% interval 0.73 to 0.94.
Gene-disease validity (ClinGen):
ClinGen rates the evidence that ZMPSTE24 causes each of these diseases.
mandibuloacral dysplasia with type B lipodystrophy (autosomal recessive): Definitive.
Homologues: Orthologues: macaque ZMPSTE24 (99% identical), pig ZMPSTE24 (97% identical), dog ZMPSTE24 (96% identical), rabbit ZMPSTE24 (95% identical), guinea pig ZMPSTE24 (95% identical), rat Zmpste24 (94% identical), mouse Zmpste24 (93% identical), chimpanzee ZMPSTE24 (91% identical), tropical clawed frog zmpste24 (82% identical), zebrafish zmpste24 (79% identical), Drosophila melanogaster ste24a (46% identical), Caenorhabditis elegans fce-1 (39% identical), and 3 more.
Diseases named in the same sentence as ZMPSTE24 in open-access papers:
ZMPSTE24 is named in the same sentence as 71 diseases in open-access papers, as found by Europe PMC text mining. Sharing a sentence is not in itself a finding about the gene and the disease. The quoted sentences say what the papers report.
progeria (44 papers, 2009 to 2025). "Variants in the ZMPSTE24 gene have been associated with progeroid syndromes, including MADB and restrictive dermopathy, as well as a severe metabolic syndrome with abnormal fat accumulation and dilated cardiomyopathy." (PMID 39273270, 2024). "Further, fibroblasts from the LMNA Δ9 progeria mouse model and hair follicle stem cells in ZMPSTE24-deficient mice have shown reduced Wnt/β-catenin signaling." (PMID 39568542, 2024). "Herein, we used ZMPSTE24-deficient mice, a lamin A defect progeria model, to investigate the ability of young MDSPCs to preserve neuromuscular tissue structure and function." (PMID 37535205, 2024). "Apart from this mutation, an alteration in the metalloproteinase Zmpste24, involved in the maturation of lamin A, causing a similar alteration than in progeria." (PMID 35306483, 2022). "Accumulation of farnesylated forms of Lamin A due to ZMPSTE24 deficiency is also toxic and leads to severe progeroid syndromes." (PMID 33918867, 2021). "Full‐length prelamin A accumulates in cells of Zmpste24‐deficient mice, which triggers nuclear shape abnormalities and several hallmarks of progeria, including bone abnormalities, rib fractures, muscle weakness, low body weight, and premature death." (PMID 32196928, 2020). "Other murine models of progeria (e.g. Lamin A- and Zmpste24-deficient, Wrn−/−, Terc−/−, PolgAmut/mut, Klotho−/−, PolG and XPD strains) also do show osteoporosis." (PMID 31553309, 2019). "Homozygous mutations in the ZMPSTE24 gene result in progeroid syndromes due to the accumulation of an farnesylated form of prelamin A." (PMID 28854936, 2017). "Compound heterozygous mutations in FACE, leading to the complete loss of function of ZMPSTE24 protease and accumulation of farnesylated prelamin A causes autosomal recessive restrictive dermopathy (RD), a progeroid syndrome associated with neonatal death." (PMID 26847180, 2016). "The most studied progeria-associated mutations involve the removal of ZMPSTE24 recognition sites, causing the accumulation around the nuclear periphery of the constitutively farnesylated protein progerin." (PMID 26900797, 2016). "For example, restrictive dermopathy, a more severe progeroid syndrome, is caused by a deficiency in ZMPSTE24 that results in a dramatic accumulation of prelamin A at the nuclear rim." (PMID 26900797, 2016). "ZMPSTE24 is a metalloproteinase mutated in human progeria and is involved in nuclear prelamin A maturation." (PMID 26214687, 2015). "A group of these laminopathies have been classified as progeroid syndromes that can be caused by mutations in LMNA or ZMPSTE24." (PMID 23804595, 2013). "Intriguingly, a case of atypical progeria associated with heterozygous compound mutations in ZMPSTE24 has been described that showed mature lamin A decrease." (PMID 23804595, 2013). "In an animal model of progeria, Zmpste24-deficient mice show hypermethylation and transcriptional silencing of rDNA genes." (PMID 23090008, 2012). "The initial full‐length sequencing of common genes implicated in progeroid syndromes, such as LaminA/C, ZMPSTE24, POLD1, and BNF1, revealed homozygous base pair mutations in exon 9 of LaminA/C c.1579C>T (p.R527C) in three patients (here referred to as MAD1, MAD2, MAD3)." (PMID 39661729, 2025). "As a pathogenic gene of progeria, whether Zmpste24 is also involved in the regulation of early development through the Hippo signaling pathway still needs to be studied." (PMID 37217512, 2023). "Therefore, elevated Sun2 can be a downstream consequence of abnormal nuclear shape caused by Zmpste24 loss in progeria cells." (PMID 37198162, 2023). "Furthermore, in vivo treatment with an FTase inhibitor (FTI) ameliorated the progeria phenotype in the Zmpste24-deficient mouse model of progeria." (PMID 34281245, 2021). "Also, a knockout of Icmt substantially improves clinical phenotypes and survival of Zmpste24-deficient mice, a model of progeria." (PMID 33526168, 2021).
progeria (continued). "This could be another overlap to NE-linked progeroid syndromes: knockdown of ZMPSTE24 also results in an enrichment of NE invaginations and the loss of ZMPSTE24 in human results in RD, the most severe NE-linked progeroid syndrome." (PMID 30140252, 2018). "The treatment with farnesyltransferase inhibitors of two progeria mouse models, ZMPSTE24-deficient mice and LMNAHG/+ knock in mice, ameliorates the disease phenotype but not completely, and all treated mice eventually develop severe phenotypes and prematurely die." (PMID 29936894, 2018). "Interestingly, heterozygosity for lamin A (Zmpste24−/− lmna+/−) largely ameliorated the progeria-like phenotypes in Zmpste24-deficient mice, suggesting that reducing prelamin A concentration by 50% was enough to reduce accelerated aging phenotypes." (PMID 22067432, 2011). "Because degenerative changes associated with progeroid syndromes may have a strong impact on stem cells, we hypothesized that the dysfunction of muscle stems cells in Zmpste24-/- progeroid mice may contribute to the loss of the cells' ability to regenerate skeletal muscle." (PMID 23531345, 2013). "Doxycycline decelerates aging in progeria mice and alleviates cell senescence in Zmpste24 KO MEFs and HGPS fibroblasts, probably via counteracting IL6 expression and NAT10‐mediated tubulin acetylation." (PMID 38686927, 2024). "We have previously shown that the number and function of MSCs and HSCs decline in the progeria mouse model, Zmpste24−/− mice." (PMID 37946040, 2023). "When cleavage by ZMPSTE24 is blocked, farnesylated and carboxyl methylated prelamin A accumulates, leading to progeroid syndromes." (PMID 37885131, 2023). "Multiple progeria mouse models, such as Zmpste24−/−, Ercc1−/−, and aP2‐cre; Ercc1fl/−, have been shown to exhibit reduced fat depots similar to naturally aged WT mice." (PMID 34734460, 2021). "As osteoarthritis and osteoporosis are strongly correlated with aging, we next turned to progeria model Zmpste24‐deleted mice." (PMID 32083237, 2020). "Zmpste24 (−/−) mice, a mouse model of progeria, exhibits dysregulation of somatotropic axis, characterized by high levels of circulating growth hormone (GH) and reductions in insulin-like growth factor-1 (IGF-1)." (PMID 23090008, 2012). "Zmpste24-null mice or human HGPS cells have been considered as segmental progeroid syndromes, in that they only partially recapitulate the phenotypes associated with normal aging." (PMID 22067432, 2011). "Studies of Zmpste24−/− mice have provided intriguing insights into the pathogenesis of progeria." (PMID 40707465, 2025). "Studies of Zmpste24−/− mice have provided further insights into the pathogenesis of progeria." (PMID 39554077, 2024). "Though the DOX treatment improves several features of Zmpste24 KO mice, the increase in lifespan is moderate, suggesting that the pathogenetic pathways underlying progeria were not all rescued." (PMID 38686927, 2024). "A similar observation has been reported in Zmpste24−/− mice, progeria mouse model." (PMID 35609021, 2022). "Moreover, we recently observed that PLA2R1 contributes to progeria phenotypes in vitro in progerin‐expressing cells and in vivo in the Zmpste24−/− murine model of progeria." (PMID 32196928, 2020). "Furthermore, Cdon and Itgb1* levels were either decreased or mislocalized in satellite cells on myofibers isolated from Zmpste24−/− mice, a model of progeria." (PMID 32103583, 2020). "In addition, pRb is downregulated in the Zinc metalloproteinase Ste24 homolog (Zmpste24)−/− progeria mouse model, and genome-wide expression analysis identified the lamin A-pRb signaling network as a major pathway affected in HGPS." (PMID 24374133, 2014). "Progeroid syndromes caused by mutations in LMNA, which encodes prelamin A as well as lamin C, and ZMPSTE24, which encodes the prelamin A processing enzyme, the zinc metalloprotease ZMPSTE24, have implicated unprocessed, farnesylated prelamin A or its variants in accelerated aging processes." (PMID 37885131, 2023).
progeria (continued). "The Zmpste24−/− HGPS and progeria mouse model showed the development of kyphosis and spontaneous bone fractures in multiple locations." (PMID 37759521, 2023). "Moreover, the elevated α‐tubulin (K40) acetylation mediated by NAT10 in progeria, is rescued by DOX treatment in the aorta tissues in Zmpste24 KO mice and fibroblasts." (PMID 38686927, 2024). "Lessel et al21 tested 50 patients with a putative diagnosis of nonclassical WS (ie, progeroid syndrome without WRN, LMNA, BANF1, and ZMPSTE24 mutations) and found causative POLD1 mutations in 8 patients." (PMID 30023403, 2018). "They did not have a therapeutic effect on the Profigin-independent progeria model mice (Zmpste24–/–) but expanded the lifespan of the HGPS model mice (Lmna+/G609G), representing the in vivo relevance of blocking Progerin–Lamin A/C interaction as a new therapeutic strategy for HGPS." (PMID 35205210, 2022).
Hutchinson-Gilford progeria syndrome (28 papers, 2009 to 2026). "Mutations of the ZMPSTE24 gene induce characteristic features of the Hutchinson-Gilford progeria syndrome, such as premature aging." (PMID 41522494, 2026). "The dissociation of accelerated aging phenotypes and cancer also applies to defects in lamin A/C, e.g. Hutchinson-Gilford progeria syndrome (HGPS) due to mutations in lamin A encoded by LMNA or its protease STE24 encoded by ZMPSTE24." (PMID 38760832, 2024). "Mutations in LMNA or ZMPSTE24 that prevent prelamin A cleavage cause the severe premature aging disorder Hutchinson-Gilford Progeria syndrome (HGPS) or the related progeroid diseases, mandibuloacral dysplasia type-B (MAD-B) and restrictive dermopathy (RD)." (PMID 33315887, 2020). "Mutations in LMNA or ZMPSTE24 that impede this prelamin A cleavage step cause the premature aging disease Hutchinson-Gilford progeria syndrome (HGPS), and the related progeroid disorders mandibuloacral dysplasia type B (MAD-B) and restrictive dermopathy (RD)." (PMID 29794150, 2018). "Related to these observations, mice deficient in the metalloprotease Zmpste24 display a progeria syndrome similar to human Hutchinson – Gilford progeria and a concomitant increase in autophagy." (PMID 19549314, 2009). "Retention of this farnesylated C terminal domain by lamin A precursors is pathologic, and mutations in both the LMNA and ZMPSTE24 genes that cause this retention are implicated in premature aging disorders, such as Hutchinson-Gilford progeria syndrome (HGPS) and DCM." (PMID 31622279, 2019). "Abnormal expression of Zmpste24 can induce premature senescence, Hutchinson-Gilford Progeria syndrome, mandibuloacral dysplasia-type B, and restrictive dermopathy." (PMID 41522494, 2026). "Zmpste24−/− mice are an established murine model of Hutchinson-Gilford progeria syndrome (HGPS), which features many musculoskeletal degenerative changes similar to those of advanced ageing." (PMID 34098983, 2021). "Another common accelerated-aging syndrome is Hutchinson-Gilford progeria syndrome (HGPS), caused by the defects in nuclear envelope proteins due to the mutations in the processing protease FACE1/ZMPSTE24 or genes encoding lamin A." (PMID 30405405, 2018). "miR-29 is up-regulated in the liver and muscles of Zmpste24-/- (Hutchinson-Gilford progeria syndrome) mice, a murine model of aging." (PMID 24659628, 2014). "Failure to cleave the prelamin A “tail”, due to mutations in either prelamin A or ZMPSTE24, results in a permanently prenylated form of prelamin A that underlies the premature aging disease Hutchinson-Gilford Progeria Syndrome (HGPS) and related progeroid disorders." (PMID 22355414, 2012). "This interferes with C-terminal cleavage of lamin A by Zmpste24 resulting in a permanently farnesylated lamin A, termed progerin, which acts in a dominant fashion to promote a range of accelerated aging phenotypes comprising Hutchinson Gilford progeria syndrome (HGPS)." (PMID 36260869, 2022). "In addition, heterozygosity of p65/RelA in a mouse model of Hutchinson-Gilford Progeria Syndrome (Zmpste24-/-) resulted in attenuated aging pathology and a prolonged lifespan, linked in part to a reduced systemic inflammatory response and a reduction in ATM/NEMO-mediated NF-κB activation." (PMID 32201398, 2020). "For example, increased ATM phosphorylation and nuclear-localized NEMO were found in the Zmpste24-/- mouse model of Hutchinson-Gilford progeria syndrome (HGPS), where accumulation of nuclear prelamin-A leads to a perturbation of NF-κB signaling." (PMID 32201398, 2020).
Hutchinson-Gilford progeria syndrome (continued). "The deficiency of ZMPSTE24 could induce Hutchinson-Gilford progeria syndrome (HGPS), and it has been found that the expression of ZMPSTE24 is decreased in the articular cartilage of OA." (PMID 40453080, 2025). "Hutchinson-Gilford progeria syndrome (HGPS) is caused by progerin, an internally truncated prelamin A that does not undergo the ZMPSTE24 processing step that releases prelamin A’s farnesylated carboxyl terminus; consequently, progerin remains farnesylated." (PMID 40707465, 2025).